TNF (tumor necrosis factor)
Diseases named in the same sentence as TNF in open-access papers (continued):
Sharing a sentence is not in itself a finding about the gene and the disease.
COVID-19 (continued). "The cytotoxic effect of NK cells from COVID-19 patients has been found to be antagonized by reduced expression of CD107a, ksp37, granulysin, and granzyme B; such NK cells display impaired production of chemokines, IFN-γ, and TNF-α, among others." (PMID 35883618, 2022). "Recently, two patients with ARDS mediated by COVID-19 were treated with ex vivo expanded allogeneic Tregs, resulting in symptom improvement, rapid decrease in inflammatory markers (IL-6, IL-12, TNF-α, IFN-γ) and no adverse effects related to the treatment." (PMID 36499448, 2022). "TNF and IL6 are recognized as major factors in the systemic inflammatory immune response, and overexpression of these factors leads to respiratory diseases, including COPD and COVID-19." (PMID 36615255, 2022). "It is interesting that the level of β-glucan was not different in COVID-19 patients with mild, moderate, or severe disease, but the levels of TNF-α, IL-8, and LPS significantly increased with increasing disease severity." (PMID 36297092, 2022). "Significantly elevated levels of inflammatory cytokines TNF-α, IL-1, IL-6, and IL-10 have been documented in cases of severe COVID-19 compared to cases of non-severe disease." (PMID 36282812, 2022). "In SARS-CoV-2 infected lung, presence of IL-1β, TNFα, IL-6, and IL-8 indicate IL-17 induced MAPK and NF-κB mediate signaling; MAPK was shown to be activated during the acute phase of SARS-CoV-2 infection in nasopharyngeal swabs of severe COVID-19 patients." (PMID 36136963, 2022). "As a result, neutralizing drugs targeting TNF-α and IFN-γ may be used in the clinical therapy of patients with COVID-19." (PMID 35663983, 2022). "Moreover, inhibition of the other two targets (TNF and VEGFA) related to the MAPK signaling pathway contribute to anti-proinflammation and anti-vascular permeability against COVID-19." (PMID 35678652, 2022). "For instance, inhibition of the CCR5-CCL4 axis by Leronlima (anti-CCR5 monoclonal antibody), or the blockade of cytokine signaling by Tocilizumab (anti-IL-6R), Adalimumab (anti-TNF-α), or Anakinra (anti-IL1R) have been shown to ameliorate, in some cases, severe COVID-19 manifestations." (PMID 35269470, 2022). "Regarding the cytokine profile of S-specific T-cells, post-COVID-19 patients with pneumonia and vaccinated subjects produced similar levels of TH1 cytokines, in particular IFNγ, IL-2, TNFα, and MIP-1β, which were significantly higher than in post-COVID-19 patients with mild symptoms." (PMID 35744768, 2022). "In this study, COVID-19, the crossover genes between RA and pyroptosis were enriched in the NLR/TLR signaling pathway, NLRP3 inflammasome complex, death-inducing signaling complex, regulation of interleukin production, NF-κB signaling, and TNF signaling." (PMID 36532040, 2022). "Added to combining selective recognized biochemical markers of COVID-19 severity (ANC, CRP, LDH, BUN and ferritin), the triad of elevated serum IL-10, PD-L1 and TNF-α improved the current model accuracy to predict the severity of the disease, through the stepwise linear regression model." (PMID 35529862, 2022). "In severe COVID-19, decreased pulmonary function is connected to elevated levels of systemic IFN-γ and TNF-α, and analysis of immune cells isolated from bronchoalveolar lavage fluid suggests T cell dysfunction potentially exacerbates tissue damage in severe cases." (PMID 35617421, 2022). "Here, we report that plasma exosomes of COVID-19 patients contain SARS-CoV-2 double stranded RNA (dsRNA) and stimulate robust production of interleukin-6 (IL-6), IL-8, tumor necrosis factor-α (TNF-α), and other inflammatory cytokines and chemokines by human peripheral mononuclear cells." (PMID 36526691, 2022). "TNFα is an important cytokine involved in immunity and known to act as an amplifier of inflammation while IL6 was identified as the most correlated cytokine to severe and critical COVID-19 conditions." (PMID 35941890, 2022).
COVID-19 (continued). "IFN-α and TNF-α concentrations were also significantly higher in non-severe COVID-19 compared to healthy controls." (PMID 35422799, 2022). "There were reduced frequency and an activated phenotype of circulating MAIT cells in COVID-19 patients regardless of disease severity, as demonstrated by high levels of IL-17A, TNF-α, CD38, CD69, and HLA-DR expression." (PMID 36034704, 2022). "The data from inflammatory bowel disease (IBD) patients with COVID-19 revealed that among 116 patients who received anti-TNF therapy, 99 patients recovered without hospital admission." (PMID 35619180, 2022). "Increased production of TNFα by CD4+ T cells and CD8+ T cells in response to COVID-19 plasma exosomes may contribute to differentiation of Th17 T cells." (PMID 36526691, 2022). "Baseline NfL levels were mostly comparable between the TNF-α tertiles, only the highest severe COVID-19 TNF-α tertile group was elevated compared with the lower tertile of the severe COVID-19 group, and the middle and lower mild COVID-19 group." (PMID 35938070, 2022). "Patients with COVID-19 also display selective induction of the macrophages that produce IL-6, but not TNF-α and IL-1β, and this then directly promotes lymphocyte necrosis." (PMID 35464491, 2022). "The remaining post-COVID-19 signature shows good agreement with single-cell RNA sequencing data and contains, among others, proteins related to TGFβ signaling, maintenance of the ECM (TGFβ1, BMP-6, MMP1, MMP7), and TNF-signaling (TNFα, TWEAK)." (PMID 36405747, 2022). "The cytokine profile in COVID-19 is explained by increasing interleukin IL-2, IL-6, IL-7, interferon-γ (INF-γ) inducible protein 10, granulocyte colony-stimulating factor (GCS-F) and tumor necrosis factor-α (TNF-α)." (PMID 35806919, 2022). "TNF-, IL-2, IL-6, IL1B, IL7, IL10, IFN-, GCSF, CXCL10, CCL2, ferritin, D-dimer, fibrinogen, leukocytosis, and C-reactive protein (CRP) levels are significantly higher in critically ill COVID-19 patients." (PMID 35645351, 2022). "However, we need to accumulate cases similar to our case to evaluate the effectiveness and safety of the combination therapy of anti-TNFα agents and immunosuppressive drugs for patients with IBD who have COVID-19." (PMID 36417106, 2022). "Across all the soluble proinflammatory markers we examined, ICAM, IL-1β, IL-4, IL-6, TNFα, and Syndecan showed a statistically significant positive correlation between cytokine or epithelial marker and antibody quantity regardless of COVID-19 disease severity." (PMID 36865568, 2022). "Furthermore, Ruxolitinib, a JAK1/JAK2 inhibitor acting downstream of JAK-dependent chemokines/cytokines such as IFN-γ, IL-1β, IL-6, TNF, G-CSF, CXCL9, and CXCL10, has shown promising results in treating COVID-19." (PMID 35269470, 2022). "Given that plasma cytokine levels decrease after SARS-CoV-2 infection while IL-1β, IL-6, and TNF remain stable in individuals with ongoing PASC, we next asked whether there are patterns in active COVID-19 that provide a mechanistical link to this observation." (PMID 35732153, 2022). "For the majority of these cytokines and chemokines, including those that are typically associated with macrophage activation syndrome (IL-6, IL-18, IFN-γ, TNF-α, CXCL9), the increase was less pronounced in COVID-19 critical condition than in macrophage activation syndrome patients." (PMID 35645351, 2022). "Patients with severe COVID-19 exhibit substantial immune changes including lymphopenia and increased blood levels of inflammatory biomarkers such as C-Reactive Protein (CRP), IL-1β, TNF-α, IL-8, and IL-64–8." (PMID 35064122, 2022). "In the acute COVID-19 group, younger patients had higher levels of TNF-α, and patients without comorbidities had higher levels of TNF-α, IL-4 and IL-2 (p<0.05)." (PMID 35846757, 2022). "In addition, peripheral blood immune cells from severe COVID-19 patients exhibit diminished type I and III IFN responses but enhanced proinflammatory IL-6 and TNF-α responses." (PMID 35832809, 2022).
COVID-19 (continued). "In this study, through network pharmacology, molecular docking, target analysis, and tissue analysis, it can be concluded that Xiyanping injection and andrographolide sulfonates such as compound III in the treatment of COVID-19 mainly act on HSP90AA1, CAT, TNF, FOS, and other targets." (PMID 35818408, 2022). "Multivariate COX regression analysis revealed that NEAT1 is an independent predictor for survival among COVID-19 patients with an odds ratio of 7.48 and 95% CI (1.03 - 36.08) (P=0.02) while (male sex, smokers, CCL2, TNF-α, and IL-6) were cofactors affecting overall survival." (PMID 35982898, 2022). "Functional clusters identified among Treg cells showed high proportion of cells with simultaneous production of different combinations of TNF-α, IL-2, CD107a, and IFN-γ (which have been found before in the entire population of CD4+ cells) at time-point I in severe post-COVID-19 patients." (PMID 35757700, 2022). "In COVID-19 patients, HMGB1 can be released from dying cells and functions as a pro-inflammatory inducer to bind with TLR4, leading to the production of IL-1β, IL-6, and TNF-α." (PMID 35832809, 2022). "Currently, multiple biomarkers in COVID-19 have been identified, such as leukocytes, C-reactive protein (CRP), procalcitonin (PCT), lactate dehydrogenase (LDH), ferritin, and cytokines (IL-2R, IL-6, IL-8, IL-10, and TNF-α)." (PMID 34573984, 2021). "In the hyperinflammatory phase, patients with severe COVID-19 exhibit higher levels of IL-2, IL-6, IL-7, IL-10, IP-10, MCP1, TNF-α, macrophage inflammatory protein 1 alpha (MIP1A), and granulocyte-colony stimulating factor (G-CSF) than patients with moderate infections (early inflammatory phase)." (PMID 34220861, 2021). "The cytokines interleukin 6 (IL-6), interleukin 1 beta (IL-1β), tumor necrosis factor alpha (TNF-α) and chemokine C–C motif ligand 2 (CCL2), 3 (CCL3), and 5 (CCL5) are upregulated and represent potential targets for treatment of patients with COVID-19." (PMID 33521616, 2021). "The levels of IL1-β, IL-6, IL-8 (p < 0.0001, for each), and TNF-α (p < 0.01) were significantly higher in the critical COVID-19 patients than in the mild COVID-19 and non-COVID-19 healthy controls." (PMID 34276659, 2021). "As shown by a study on 452 patients, markedly elevated levels of IL-6 and slightly enhanced levels of TNF and IL-2R, while no marked change of IL-1β, were observed in COVID-19 patients." (PMID 33907514, 2021). "High plasma levels of tumor necrosis factor-α (TNF-α), IL-1β, IL-6, and IL-8 have been confirmed in COVID-19, especially in non-survivors and in critically ill patients." (PMID 34177896, 2021). "Interwoven with Th17, TNF-α, and IFN may be the link between psoriasis exacerbation and COVID-19 vaccines, yet further investigations are required to unravel the immunologic reactions." (PMID 35004790, 2021). "Like COVID-19, increased production of multiple pro-inflammatory chemokines and cytokines is a prominent feature of mycobacterial IRIS, including increased production of TNF-α and IL-6." (PMID 33841434, 2021). "COVID-19 is characterized by cytokine storms, and patients are positive for cytokines, such as monocyte chemoattractant protein 1 (MCP1), macrophage inflammatory protein (MIP)1α, interleukin (IL)-6, IL-2, IL-7, IL-10, and tumor necrosis factor alpha (TNF-α)." (PMID 34419143, 2021). "A reduction in serum levels of IL-6, IL-1β, and TNF-α, rapid recovery of circulating T and B cell frequencies, and increased antibody production against the SARS-CoV-2 spike protein has been reported in severe COVID-19 cases treated with this agent." (PMID 34590796, 2021).
COVID-19 (continued). "More recently, single-cell RNA sequencing analysis has shown that IFN-I responses co-occur with TNF- and IL-1-driven inflammatory responses in PBMCs from patients with severe COVID-19, rather than mild COVID-19." (PMID 34001144, 2021). "Levels of IL-6 and TNF-α increased significantly in the acute phase of SARS-CoV-2 infection, in good agreement with previous observations showing elevated IL-6 in the setting of severe COVID-19." (PMID 34884175, 2021). "Our data from network pharmacology also suggested that five signaling pathways including TNF, HIF-1α, TLR, apoptosis-related, and VEGF signaling may be the therapeutic pathways in Quercetin treatment to COVID-19-induced AKI." (PMID 33444408, 2021). "Among the inflammatory parameters, our systematic review and analysis demonstrated a marked elevation in the level of circulating IL-6 and TNF in severe COVID-19 and MERS patients in comparison to non-severe groups." (PMID 34046036, 2021). "Lymphopenia is one of the markers of TNF-α and IFN-γ shock or severe COVID-19." (PMID 34946543, 2021). "While CXCL9, CXCL10 and CXCL11 expression levels were increased both in moderate and severe disease compared to healthy levels, IL1β, IL6, TNF as well as CCL2, CCL3, CCL4 and CCL7 were expressed at higher levels in lung macrophages from patients with severe COVID-19." (PMID 34367190, 2021). "Indeed, studies have demonstrated the presence of elevated levels of inflammatory factors such as interleukin-6 (IL-6), tumor necrosis factor-α (TNF-α), and IL-1β, in patients with COVID-19." (PMID 34444014, 2021). "Following molecular docking analysis, in silico investigation helped identify the anti-UCEC/COVID-19 pharmacological bio targets of PLB, including mitogen-activated protein kinase 3 (MAPK3), tumor necrosis factor (TNF), and urokinase-type plasminogen activator (PLAU)." (PMID 34712201, 2021). "Higher TNF-α levels have been observed in patients with severe COVID-19, but this finding has not been universal." (PMID 34938289, 2021). "LH works through the suppression of viral loads in the cytoplasm and cellular membrane and replication of COVID-19 and H1N1 and can inhibit the release of tumor necrosis factor-alpha (TNF-α), interleukin-6 (IL-6), and macrophages, all of which are components in the cytokine storm." (PMID 34831757, 2021). "A significant increasing trend of IL-1β, IL-1ra, IL-2, IL-4, IL-5, IL-6, IL-7, IL-8, IL-10, IL-12(p70), IL-15, IL-17, FGF-b, G-CSF, GM-CSF, IFN-γ, IP-10, MCP-1, MIP-1α, PDGF, TNF-α, and VEGF was observed in the three groups (Controls ≤ Mild COVID-19 ≤ Severe COVID-19)." (PMID 34675240, 2021). "In this regard, the increase of blood inflammatory markers (e.g., CRP, IL-6, TNF-α, IL-1, etc.)in GBS tested cases may reinforce the hypothesis of a systemic inflammatory storm in COVID-19." (PMID 32840686, 2021). "Based on ROC analysis, nine biomarkers (TNF-α, IL-10, MIG, IL-6, IP-10, M-CSF, G-CSF, GM-CSF, IFN-α2) were established as good early predictors for COVID-19 patients who may require ICU admission." (PMID 34858428, 2021). "For example, higher levels of Klebsiella, Streptococcus, and Ruminococcus gnavus in COVID-19 patients have been correlated with increases in the levels of pro-inflammatory cytokines (IFN-γ and TNF-α), leading to a cytokine storm and activation of T helper cells (Th1)." (PMID 34578858, 2021). "With that, the comparison of blood levels of IL-1, IL-1RA, IL-6, IL-8, IL-18, and TNF-a in ARDS COVID-19 and bacterial sepsis revealed no significant changes." (PMID 34299201, 2021). "In conclusion, we showed an increase in the serum levels of cytokines, including IL1-β, IL-6, IL-8, and TNF-α in ICU patients relative to mild COVID-19, while RANTES serum levels were increased in the mild, not ICU patients." (PMID 34276659, 2021).
COVID-19 (continued). "The results showed that TNF-α was negatively correlated with SDANN (r = –0.6680, P < 0.0001) and SDNN (r = –0.2767, P = 0.224) and positively correlated with LF/HF (r = 0.4109, P = 0.0005) in COVID-19 patients." (PMID 34093217, 2021). "Severe COVID-19 patients show increased levels of the granulocyte colony-stimulating factor (G-CSF), IL-2, IL-6, IL-10, monocyte chemo-attractant peptide (MCP)-1), macrophage inflammatory protein 1α (MIP1α) and TNF-α." (PMID 33927728, 2021). "Furthermore, the downstream factors of TLR7 and BTK in TLR pathway, such as MYD88, IRF7, NFKB1, and JUN, and cytokines (TNF, IL1B, and IL18) were elevated in men with severe COVID-19." (PMID 34330889, 2021). "HDLs from COVID-19 patients displays a blunted protective effects against HUVEC permeability, VE-cadherin peripheral belt the cell–cell disruption and apoptosis induced by TNFα." (PMID 33504824, 2021). "Interestingly, comparing the frequency of double-positive (IFNγ+ TNF+) CD4+ and CD8+ T cells within individuals, these were higher in both COVID-19 patients and close contacts than in healthy controls." (PMID 33741972, 2021). "In patients with severe COVID-19, higher interleukin (IL)-6, IL-10, granulocyte-colony stimulating factor (G-CSF), monocyte chemoattractant protein 1 (MCP1), macrophage inflammatory protein (MIP)1α, and tumor necrosis factor (TNF)-α were reported." (PMID 34440608, 2021). "We found that statins may be effective by ameliorating endothelial dysfunction triggered by cytokine storm cytokines/chemokines (IL-6, TNF-α, IL-1β, CCL2, interferons, and related factors) released from COVID-19 patients." (PMID 34253708, 2021). "For example, three studies out of eight showed a significant elevation on TNF level in severe COVID-19 patients compared to non-severe groups." (PMID 34046036, 2021). "The hyper inflammation and cytokine storm, common in COVID-19 patients, with an elevation in IFN-γ, IL-1β, IL-6, IL-17, and TNF, promotes muscular proteolysis, decreased protein synthesis, and satellite cells dysfunction, possibly another mechanism of muscle wasting in these individuals." (PMID 33613573, 2021). "We observed several folds of increases in the SARS-CoV-2 antigen-reactive T cells over the control T cells, indicating that DCs presenting the SMENP epitopes (CTL + COVID-19) elicited a strong anti-SARS-CoV-2 T-cell response in both CD4 and CD8 T cells (CD107a, IFN-γ, TNF-α, and IL-2)." (PMID 34451952, 2021). "A systemic inflammatory storm in COVID-19 may also contribute to the amplification of the GBS’s dysimmune process, related to increased blood inflammatory markers (e.g., CRP, IL-6, TNF-α, and IL-1)." (PMID 34078305, 2021). "Aiming at finding discriminant oral cytokines for COVID-19 status, we employed volcano plot and VIP plot, finding out seven COVID-19-related discriminant cytokines (IL-6, IL-5, GCSF, IL-2, TNF-α, GMCSF, and INF-γ), while only one (IL-12p70) for controls." (PMID 34394024, 2021). "Furthermore, the expression of CD94/NK group 2 member A (NKG2A) was increased on cytotoxic T lymphocytes (CTLs) and NK cells in COVID-19 patients, accompanied by low levels of CD107a, IFN-γ, IL-2, TNF-α, and granzyme B." (PMID 33987176, 2021). "Fifth, hypertriglyceridemia as a result of lipoprotein lipase inhibition by TNF-α is not usually reported in COVID-19." (PMID 34715834, 2021). "Studies have shown that several circulating cytokines and chemokines such as TNFα, CXCL-10, IL-6, and IL-8 are differentially expressed during SARS-CoV-2 infection, and this cytokine/chemokine storm likely contributes to the poor prognosis of COVID-19." (PMID 34531741, 2021).